SF1 (splicing factor 1)
Diseases named in the same sentence as SF1 in open-access papers (continued):
Sharing a sentence is not in itself a finding about the gene and the disease.
Hypoglycemia (continued). "Outcomes show that hypoglycemia elicits a gain of SF-1 inhibitory control of Ghrh and Ghrh-R mRNA profiles as well as loss of stimulatory influence on GLS transcription in VMNdm Ghrh neurons in the female rat." (PMID 39401164, 2024). "Data moreover substantiate VMN SF-1 regulation of circulating corticosterone, glucagon, and GH concentrations during eu- and hypoglycemia." (PMID 39024550, 2024). "As Ghrh and Ghrh-R mRNA levels were unaffected by hypoglycemia in this sex, it is likely that a SF-1-mediated suppressive tone is counterbalanced by positive stimuli." (PMID 39401164, 2024). "SF-1 stimulates baseline VMNdm Ghrh neuron PRKAA1/AMPKα1 and PRKAA2/AMPKα2 gene expression, yet causes opposite changes in these gene profiles during hypoglycemia." (PMID 39401164, 2024). "SF-1 up-regulates baseline ERα, ERβ, and GPER gene expression in this cell type, but elicits distinctive adjustments in ER variant transcription during hypoglycemia." (PMID 39024550, 2024). "Hypoglycemia augmented or reduced nitric oxide synthase and glutaminase mRNAs, responses that were attenuated by SF-1 gene silencing." (PMID 39024550, 2024). "Inhibitory effects of hypoglycemia on this gene profile were partially reversed by SF-1 siRNA pretreatment." (PMID 39024550, 2024). "SF-1 exerts glucose-dependent control of ER-alpha and G-protein-coupled ER-1 transcription, but blunts ER-beta gene profiles during eu- and hypoglycemia." (PMID 39401164, 2024). "Gene expression measurements disclose contrary GLUT2 control of VMNdm versus VMNvl GABAergic neuron SF-1 gene responses to hypoglycemia." (PMID 38902332, 2024). "This genetic approach establishes that SF-1 neurons of the VMH are a critical subset of neurons playing important roles in counterregulation against hypoglycemia in the brain." (PMID 23675313, 2013). "Hypoglycemia increased SF-1 gene expression in GABA nerve cells taken from each VMN division." (PMID 38902332, 2024). "New results described here reveal that SF-1 suppresses GLS gene expression during eu- or hypoglycemia, and support the view that this transcription factor may mediate hypoglycemic inhibition of this gene profile." (PMID 39024550, 2024). "SF-1 may thus be capable of discriminative control of vesicular versus cytoplasmic GABA production and activity in this nerve cell type during hypoglycemia; data suggest that SF-1 may inhibit the former pool while stimulating the latter." (PMID 39024550, 2024). "Stimulatory effects of hypoglycemia on this gene profile were reversed by SF-1 siRNA pretreatment." (PMID 39024550, 2024). "Thus, insight on the direction and magnitude of SF-1 regulatory impact on AMPK activity during eu- or hypoglycemia will require additional effort." (PMID 39024550, 2024). "Data show that net tissue SF-1 protein in this location was refractory to hypoglycemia." (PMID 39024550, 2024). "Results show that SF-1 expression is critical for female rat VMNdm Ghrh neuron counterregulatory neurochemical, AMPK catalytic subunit, and ER variant gene transcription responses to hypoglycemia." (PMID 39401164, 2024). "It is noted that quantifiable experimental stimulus-induced changes in SF-1 mRNA profiles, such as hypoglycemia-associated decrements in SF-1 gene expression observed here, do not provide confirmation that Ghrh SF-1 protein undergoes changes of parallel magnitude." (PMID 39024550, 2024). "Interestingly, the Sf1-Cre;Vglut2flox/flox mice exhibited impaired glucose homeostasis in the fasted condition together with blunted counterregulatory responses to insulin-induced hypoglycemia." (PMID 23675313, 2013). "In female, hypoglycemia elicits a gain of negative SF-1 regulation of ERα mRNA in this cell population, whereas in the male, SF-1 regulation of this gene profile is stimulatory irrespective of normal versus lowered circulating glucose levels." (PMID 39401164, 2024).
Hypoglycemia (continued). "Brain cell glucopenia may be directly monitored by SF-1 – expressing VMN neurons as these neurons express AMPK protein, which undergoes increased phosphorylation in response to hypoglycemia." (PMID 39024550, 2024). "The female also exhibits a switch in direction of SF-1 control of GPER, i.e. stimulatory-to-inhibitory, due to hypoglycemia; SF-1 regulation of this gene profile in the male is negative." (PMID 39401164, 2024). "Results show that SF-1 expression is critical for female rat VMNdm Ghrh neuron counterregulatory neurochemical, AMPK catalytic subunit, and ER gene transcription responses to hypoglycemia." (PMID 39401164, 2024). "The reduction in SF1 neuronal activity observed in this transgenic mouse did not compromise CRR to hypoglycemia, in contrast to previous studies in which chemogenic or optogenetic silencing of these neurons impaired recovery from hypoglycemia." (PMID 34201257, 2021). "Current research extends those findings by addressing the premise that SF-1 may impose sex-specific control of glucose-regulatory signaling, AMPK catalytic function, and estradiol receptivity in VMNdm Ghrhs population during eu- and hypoglycemia." (PMID 39401164, 2024). "The direction of SF-1 regulation of GAD2 transcription profiles is evidently dependent upon glucose status, as this control shifts from stimulatory-to-inhibitory during eu- versus hypoglycemia; elucidation of the mechanisms that mediate this directional switch will require further investigation." (PMID 39024550, 2024). "It has been described also that estrogens regulate the activity of GI neurons of the ventrolateral portion of VMH, since females showed an attenuated response to hypoglycemia compared to male mice, although in this study it is not specified if these neurons were SF1 positive cells." (PMID 34201257, 2021). "Hence, the possibility that SF-1 protein expression in this cell type may be refractory to hypoglycemia, despite decreased SF-1 transcription, should not be discounted." (PMID 39024550, 2024). "Present data show that insulin‐induced hypoglycemia (IIH) did not alter GAD65/67, nNOS, or SF‐1 protein expression in the male rat VMN." (PMID 29199177, 2017). "Our research did not address the intriguing prospect that Ghrh-R-controlled SF-1 transcriptional activity may shape, albeit in a sex-contingent manner, Ghrh-R-dependent neurotransmitter marker or AMPK gene expression patterns during eu- versus hypoglycemia." (PMID 40688570, 2025). "Interestingly, SOCS3 ablation in steroidogenic factor-1 (SF1)-expressing cells, which includes the ventromedial nucleus of the hypothalamus (VMH), reduces blood glucose levels in fed and fasted mice, even though the animals do not develop hypoglycemia." (PMID 35742928, 2022).
acromegaly (8 papers, 2020 to 2025). Acromegaly is an acquired disorder related to excessive production of growth hormone (GH) and characterized by progressive somatic disfigurement (mainly involving the face and extremities) and systemic manifestations. "Double-positive (PIT-1/SF-1) acromegaly-associated tumors exhibited a TFs activity profile typical of PIT-1–positive rather than SF-1–positive tumors, except for NR5A1, whose activity was shared by double-positive and gonadotroph PitNETs." (PMID 40813692, 2025). "Here we demonstrate that multilineage PIT1 and SF1 PitNETs can also cause acromegaly, express SSTR and respond to SRL." (PMID 37851558, 2023). "To date, there have been few studies in which the clinicopathological features of acromegaly patients with PIT1/SF1 tumors were investigated." (PMID 40421250, 2025). "PIT1/SF1 tumors, the main subtype of plurihormonal tumors in acromegaly, were previously considered rare." (PMID 40421250, 2025). "In our cohort, PIT1/SF1 tumors accounted for approximately 30.0% of acromegaly patients, which is lower than the prevalence reported in prior study." (PMID 40421250, 2025). "Additional studies are necessary to clarify whether PIT1/SF1 tumors have distinctive clinical and prognostic features in acromegaly." (PMID 40421250, 2025). "Consequently, PIT1/SF1 tumors typically present with clinical manifestations related only to excess GH in acromegaly." (PMID 40421250, 2025). "PIT1/SF1 tumors represented 30.9% (n = 29) of the acromegaly patients in this cohort." (PMID 40421250, 2025). "PIT1/SF1 tumors represent approximately 30.0% of acromegaly patients." (PMID 40421250, 2025). "With the routine application of TFs, studies have reported few acromegaly patients harboring atypical tumors that stain positive for both PIT1 and SF1 (PIT1/SF1 tumors)." (PMID 40421250, 2025). "A subtype of tumors in patients with acromegaly was found to express PIT-1 and SF-1 TFs, two markers of distinct pituitary cell lineages." (PMID 40813692, 2025). "For example, in one of our patients with confirmed acromegaly, the tissue was SF-1 positive but completely negative for PIT-1 and T-PIT." (PMID 40579705, 2025). "From transcriptomic perspective — based on gene co-regulation and pituitary TF activity — PitNETs of patients with acromegaly that co-express PIT-1 and SF-1 represent a subtype of PIT-1 lineage tumors, and the molecular data do not support classifying them as multilineage tumors." (PMID 40813692, 2025). "PIT1/SF1 tumors, as a specific subtype of plurihormonal tumors, are not rare among acromegaly patients." (PMID 40421250, 2025). "Transcriptomic group 1 includes ~20% of acromegaly patients with GNAS mutations-negative, mainly densely granulated tumors that co-express GIPR and NR5A1 (SF-1)." (PMID 36497102, 2022).
adrenal tumors (7 papers, 2011 to 2022). "In particular, this has been noted in childhood adrenal tumors where an increased copy of the SF-1 gene is associated with tumorigenesis." (PMID 25889798, 2015). "A panel of markers (CD56, vimentin, melan-A, inhibin-α, synaptophysin, chromogranin and SF-1) are used to establish the origin of adrenal tumors." (PMID 34803919, 2021). "In adrenal tumors, EG-VEGF interacts with steroidogenic factor 1 (SF-1) inducing a nuclear expression of EG-VEGF which proved to have a strong impact on prognosis for patients with adrenal tumors." (PMID 28386275, 2017). "SF-1 overexpression establishes the adrenal cortex as the origin of adrenal tumors, and the intensity of SF-1 staining is related to prognosis." (PMID 25889798, 2015). "In addition, steroidogenic factor 1 (SF-1), another gene that plays an essential role in promoting the occurrence and development of adrenal tumors, is of great significance to the growth and migration of adrenal tumor cells." (PMID 35983531, 2022). "Given the role of SF-1 in adrenocortical cellular development, the lack of SF-1 staining in sarcomatoid adrenal tumors suggests an alternative pathway of development for these tumors." (PMID 25889798, 2015).
gonadotroph adenomas (6 papers, 2013 to 2024). "In this case, some oncocytomas and null cell adenomas is actually gonadotroph adenomas with positivity of transcription factors SF-1." (PMID 31455412, 2019). "NOS1 and DAX1, regulated by and/or regulating the transcription factor SF-1, are highly expressed in human gonadotroph adenomas." (PMID 23756599, 2013). "Considering the threshold of hormone-positivity is very low in our study, we believe it should be further validated whether single SF-1immunostain is sufficient to characterize gonadotroph adenomas and whether current antibody for SF-1 is a reliable." (PMID 34589436, 2021). "Similarly to the rat tumors, several downstream targets of SF-1 were found to be highly expressed in human gonadotroph adenomas by array analysis." (PMID 23756599, 2013). "A gonadotroph adenoma positive for SF-1, and lacking FSH and LH, was the most frequently found discrepancy." (PMID 38248047, 2024). "The majority of mismatched cases were gonadotroph adenomas (43 patients, 86.0%) with stains positive for SF-1 but negative for both FSH and LH." (PMID 34589436, 2021).
adrenal hypoplasia (5 papers, 2007 to 2020). "Targeted mutagenesis of β-catenin in SF1+ cells causes late onset adrenal hypoplasia, presumed to be the result of stem/progenitor cell pool depletion." (PMID 25798129, 2015). "The atypical orphan NR Dax-1 binds to and represses SF-1 target genes; however, loss-of-function mutations of Dax-1 also cause adrenal hypoplasia, suggesting that Dax-1 may function as an SF-1 coactivator in some circumstances." (PMID 30238005, 2018). "Children (n = 22) who had been diagnosed with salt-losing forms of adrenal hypoplasia (19 isolated cases, 3 familial), and who were negative for mutations in DAX1 (NR0B1) and SF1 (NR5A1)." (PMID 17223989, 2007).
disorders of sex development (5 papers, 2008 to 2024). "In humans, SF1 mutations were first described in two patients with 46, XY disorders of sex development (DSD) who presented with adrenal failure and gonadal dysgenesis with persistent Müllerian derivatives." (PMID 39050587, 2024). "NR5A1/SF-1 variants are associated with a broad spectrum of phenotypes across individuals with disorders of sex development (DSDs)." (PMID 39337600, 2024). "In human embryogenesis, loss of SRY (sex determining region on Y), SOX9 (SRY-related HMG box 9) or SF1 (steroidogenic factor 1) function causes disorders of sex development (DSD)." (PMID 21412441, 2011). "In contrast, it is emerging that variations in SF-1 can be found in association with a range of human reproductive phenotypes such as 46,XY disorders of sex development (DSD), hypospadias, anorchia, male factor infertility, or primary ovarian insufficiency in women." (PMID 21078366, 2011). "We have analyzed the gene encoding SF1 (NR5A1) in a cohort of 27 patients with 46,XY disorders of sex development (DSD) from the German network of DSD." (PMID 17694559, 2008).
prostate carcinoma (5 papers, 2019 to 2025). A carcinoma that arises from epithelial cells of the prostate gland. "Moreover, SF-1 is sufficient and necessary to promote prostate cancer cell growth and proliferation and also mediate the growth of BCaPT10 prostate cell xenografts within a steroid-depleted environment." (PMID 33750894, 2021). "Furthermore, SF-1 was required for steroid-mediated cell growth in prostate cancer cells." (PMID 31212954, 2019). "The current literature on the functions of NRs in prostate cancer indicate that DAX1, SHP, RARβ/γ, FXRs, LXRs, VDR, ERβ, ERRβ/γ, and MR can play antioncogenic roles, while PPARγ, RORγ, SF-1, LRH-1, Erα, and GR, as well as AR, can play oncogenic roles." (PMID 31212954, 2019). "The absence of SF1 involvement contrasts with its established role in prostate cancer, highlighting tissue-specific regulatory networks." (PMID 40544998, 2025). "Their results show that SF-1 expression is absent in benign prostatic cells but present in aggressive prostate cancer cell lines." (PMID 33750894, 2021). "SF-1, a key regulator of steroidogenesis in normal endocrine tissues, is not expressed in benign cells, but present in prostate cancer cell lines." (PMID 31212954, 2019).
germ cell tumor (4 papers, 2015 to 2026). A benign or malignant, gonadal or extragonadal neoplasm that originates from germ cells. "Our previous study found lower incidence of TGCT (testicular germ cell tumors) in DND1Ter mutant mice that express reduced SF1." (PMID 33202710, 2020). "Immunophenotypically, tumors express sex cord-stromal markers, including steroidogenic factor-1 (SF-1) and inhibin, and frequently co-express epithelial membrane antigen and CD30 while lacking germ cell tumor markers." (PMID 41898873, 2026). "Newer markers for the sex cord stromal family of tumors include SF-1 and FOXL2, which are highly specific and are not expressed by germ cell tumors." (PMID 26742984, 2015).
ovarian tumor (4 papers, 2013 to 2024). "We examined loss of heterozygosity (LOH) and promoter methylation as potential mechanisms that may explain the loss of SF-1 protein in ovarian tumor tissues." (PMID 23291911, 2013). "Identification of a somatic mutation and/or methylation together with LOH in the same tumor, may explain the loss of SF-1 protein reported in ovarian tumor tissue." (PMID 23291911, 2013). "These molecular abnormalities may partially explain the loss of SF-1 protein, and contribute to the model of SF-1 as an ovarian tumor suppressor." (PMID 23291911, 2013). "The data presented herein support such a role for human SF-1, and may provide a molecular mechanism to partially explain the loss of SF-1 protein reported in both ovarian tumors and ovarian cancer cell lines." (PMID 23291911, 2013). "In the current study, we considered two molecular hypotheses of SF-1 protein loss in ovarian tumors: LOH and increased methylation." (PMID 23291911, 2013). "Thus methylation may be a major molecular mechanism leading to the reported loss of SF-1 protein in ovarian tumors." (PMID 23291911, 2013). "Therefore, the frequently observed genetic (LOH/substitution) events at the NR5A1 locus may significantly contribute to the reported loss of SF-1 protein in ovarian tumor tissue." (PMID 23291911, 2013). "The CHEK2 c.1100delC mutation was found in a single case of a primary ovarian tumor with the FOXL2p.C134W somatic mutation, morphologically consistent with AGCT and positive by IHC for inhibin, FOXL2, calretinin, and SF1." (PMID 35267514, 2022). "This analysis should include the NR5A1 gene promoter, since SF-1 protein expression is lost in both human ovarian tumors and tumor cell lines." (PMID 23291911, 2013). "The existence of both genetic and epigenetic NR5A1 gene abnormalities in ovarian tumors further suggest that SF-1 is a common and important target in ovarian carcinogenesis." (PMID 23291911, 2013). "Further large-scale studies should provide additional insights into the mechanism whereby ovarian tumors, which contain functioning stroma with a high serum estrogen level and high expressions of P450 aromatase and SF-1, affect the prognosis and clinical outcomes of ovarian tumor patients." (PMID 26576867, 2015). "Based on these facts, it is reasonable to suggest that the overexpression of SF-1 may promote estrogen biosynthesis through regulation of P450 aromatase expression in ovarian tumors with functioning stroma, and this in turn induces a high serum E2 level." (PMID 26576867, 2015). "These cases suggest that overexpression of SF-1 may promote estrogen biosynthesis through regulation of P450 aromatase expression in ovarian tumors with functioning stroma; this in turn induces high serum E2 levels in postmenopausal women with common epithelial ovarian tumors." (PMID 26576867, 2015). "Expression of the SF-1 protein, a potential ovarian tumor suppressor, has been demonstrated in normal OSE cells, but is lost in most ovarian tumors and ovarian tumor cell lines." (PMID 23291911, 2013). "We then utilized immunohistochemistry to demonstrate that the vast majority of the human ovarian tumor tissues examined do not express SF-1 protein (unpublished data)." (PMID 23291911, 2013).